CXCL16 (C-X-C motif chemokine ligand 16)
Diseases named in the same sentence as CXCL16 in open-access papers (continued):
Sharing a sentence is not in itself a finding about the gene and the disease.
breast carcinoma (continued). "MSCs migrate towards breast cancer cells via hypoxia-induced interleukin 6 (IL6) secretion and towards primary breast tumors via the hypoxia-inducible factor alpha (HIFα)-dependent secretion of CXCL16." (PMID 29642534, 2018). "Furthermore, neutralizing antibody directed against CXCL16, alone or in combination with CXCR4 antagonist, significantly inhibited the migration of patient-derived breast cancer cells in our 3D CAF aggregate system." (PMID 28649646, 2017). "It has been previously shown that CXCL16 is responsible for attracting tumor-specific T cells to the irradiated tumor site and is a crucial component of the successful combination of radiotherapy and anti-CTLA4 treatment in a mouse breast cancer model." (PMID 25127546, 2014). "We discovered no role for CXCL16 in the proliferation of breast cancer cell lines in our study, unlike other tumor suppressor studies." (PMID 24864132, 2014). "The effect of CXCL16 on cancer cell migration may be increased by chronic hypoxia, which increases HIF-1-dependent CXCR6 expression and thus the sensitivity of tumor cells to sCXCL16, as shown in breast cancer MDA-MB-231 cells." (PMID 33800554, 2021). "These are speculative explanations for how CXCL16 appears not to affect proliferation of breast cancer cells." (PMID 24864132, 2014). "It has been speculated that tumor cell lines are normally transformed and have multiple genetic alterations, which may contribute to the noneffect of CXCL16 on the breast cancer proliferation." (PMID 24864132, 2014). "The screening results showed that none of the receptors for Cx3cl1 (CX3CR1), Cxcl16 (CXCR6), Ccl17 (CCR4, DARC, CCR10) or IL6 (IL6R) was more expressed in basal B compared to basal A or luminal breast cancer cells." (PMID 38055067, 2023). "We subsequently performed an angiogenesis protein array and found that CXCL16, amphiregulin and tissue inhibitor of metalloproteinases (TIMP1) were expressed at high levels in the TN but not the ER+ breast cancer CAF supernatants." (PMID 27725631, 2016).
prostate carcinoma (41 papers, 2009 to 2026). A carcinoma that arises from epithelial cells of the prostate gland. "Studies from our and other labs have revealed that CXCR6/CXCL16 axis is expressed in inflammation associated tumors, prostate cancer, breast cancer, lung cancer, renal cancer, colorectal cancer, pancreatic ductal carcinoma, nasopharyngeal carcinoma, and malignant melanoma." (PMID 30792527, 2019). "Microarrays of tissues from prostate cancer patients showed high expression of CXCL16 in tumour compared with adjacent normal tissues, and the expression of CXCL16 was related to tumour growth." (PMID 35869057, 2022). "In prostate cancer, high CXCL16 and CXCR6 expression is an independent predictor of poor clinical prognosis." (PMID 35468838, 2022). "Similar to this, the role of CXCL16 in supporting cell migration via αVβ3 integrin in prostate cancer cells is established." (PMID 34298782, 2021). "In NSCLC and prostate cancer, the increase of CXCL16 and CXCR6 is related with the poor prognostic features of patients." (PMID 33763372, 2021). "Another important element promoting prostate cancer bone metastases is CXCL-16, whose expression on prostate cancer cells led to the recruitment of mesenchymal stem cells (MSCs) from bone marrow, which express the CXCR6 chemokine receptor." (PMID 33535541, 2021). "In vitro or in vivo models demonstrated that IL6, IL8, and CXCL16 can promote prostate cancer growth or metastasis." (PMID 34638448, 2021). "This tropism was further elucidated in a study from 2013 that unveiled an active recruitment of MSCs to prostate cancer via prostate cancer-secreted CXCL-16." (PMID 31214172, 2019). "Another less prominently studied pathway is the CXCR6/CXCL16 molecular axis recently involved in homing of prostate cancer cells to the bones." (PMID 31338489, 2019). "We have also shown the role of CXCL16 in supporting cell migration via αVβ3 integrin in prostate cancer cells." (PMID 30792527, 2019). "In this study, we show involvement of CXC chemokine receptor 6 (CXCR6) and its only natural ligand CXCL16 in pathobiology of prostate cancer (PCa)." (PMID 26799186, 2016). "Studies have shown chemokines like CXCL13 and CXCL16 independently enhance cell proliferation as well as invasive capacity of prostate cancer cells and human trophoblast cells." (PMID 25888629, 2015). "In prostate cancer cell lines, CXCL16 induced the expression of progangiogenic cytokines IL-8 and VEGF, while CXCR6 expression on implanted tumor cells lead to increased blood vessel formation in mice." (PMID 26021984, 2015). "Previously, we demonstrated that CXCL16/CXCR6 chemokine axis induces prostate cancer progression by the AKT/mTOR signaling pathway." (PMID 25909173, 2015). "For example, elevated CXCL16 expression was observed in several prostate cancer cell lines, as well as in prostate tumors from humans, with much higher expression found in the more aggressive PC3 cells relative to the less aggressive LNCaP cells." (PMID 24533143, 2014). "Different from our previous study in human prostate cancer, there were a considerable proportion of cases (19/33) that also coexpressed CXCL16, the sole ligand for CXCR6." (PMID 24897301, 2014). "CXCR6 along with CXCL16 mediates pro-tumorigenic effect on prostate cancer cells by inducing the migration and proliferation of tumor associated leukocytes." (PMID 24259307, 2013). "Of additional related interest, a recent study reported induction of CXCL16 in bone stroma conditioned by prostate cancer cells, and elevated serum levels of CXCL16 in patients with metastatic prostate cancer." (PMID 19690611, 2009). "We found high expression for CXCL16 in chronic prostatitis, pre-neoplastic lesions, and primary prostate cancer surrounded by reactive, i.e. post-inflammatory stroma." (PMID 19690611, 2009). "Screening for 37 chemokines in prostate cancer cell lines and xenografts revealed CXCL16, the ligand for the receptor CXCR6, as the most consistently expressed chemokine." (PMID 19690611, 2009).
prostate carcinoma (continued). "One paper, also like ours, demonstrated a positive correlation between CXCR6 levels and Gleason scores, reported CXCL16 expression in prostate cancers, and showed increased secretion of CXCL16 from prostate cell lines after treating with TNF-α." (PMID 19690611, 2009). "In order to investigate the roles of chemokines in prostate cancer, we screened prostate cancer cell lines and xenografts for expression of mRNAs for 37 chemokines, and found that the mRNA for CXCL16 was the most consistently expressed." (PMID 19690611, 2009). "In addition, CXCL16 can promote the proliferation of PC3 cells and high expression of CXCL16 correlates with high‐stage and high‐grade prostate cancer." (PMID 36608258, 2023). "Interestingly, a recent report showed that the CXCL16-regulated feedback mechanism is critical for the activation of NF-κB in prostate cancer cells." (PMID 35335970, 2022). "This hypothesis is supported by preclinical models demonstrating recruitment of MSCs to prostate cancer promotes metastasis through a CXCL16/CXCL12-dependent mechanism." (PMID 28493842, 2017). "One potential candidate is AKT/mammalian target of rapamycin (mTOR) signaling pathway because CXCL16 has been reported to promotes prostate cancer progression by activating the AKT/mTOR signaling pathway, which is abolished by rapamycin, a mTOR inhibitor and an anti-aging and anti-cancer drug." (PMID 27191747, 2016). "For example, prostate cancer cell lines show variations in their MMP profile post CXCL16 addition." (PMID 25888629, 2015). "Furthermore, the expression of CXCR6 and its ligand CXCL16 in prostate cancer correlated with prognosis and CXCL16 enhanced the growth of CXCR6 expressing cancers." (PMID 24259307, 2013). "In addition to the association of CXCL16/CXCR6 with inflammatory infiltrates in prostate, our initial impression from analyzing more than 80 cases of prostate cancer was that expression of CXCL16 was highest in cancer cells surrounded by reactive stroma." (PMID 19690611, 2009). "Similar to CXCL16, an elevated CXCR6 expression is also associated with poorer overall survival for patients with cervical cancer, clear cell renal cell carcinoma, Ewing sarcoma family tumor, gastric cancer, gastrointestinal stromal tumors, hepatocellular carcinoma (p = 0.064), and prostate cancer." (PMID 33800554, 2021). "Our previous studies have demonstrated that CXCL16 signaling through CXCR6 may contribute to prostate cancer progression by serving as a proliferative signal and as a regulator of invasion; however, its role and mechanism of in BC development is still kept unsettled." (PMID 25909173, 2015). "In addition, CXCL16 enhanced proliferation of prostate cancer cell lines expressing CXCR6." (PMID 19690611, 2009). "In prostate cancer, inflammatory cytokines derived from the adjacent infiltrating CXCR6-positive T cells stimulate the production of CXCL16 by cancer cells and CXCL16 enhances the growth of CXCR6-expressing cancers and primary T cells." (PMID 36311728, 2022). "Mechanistically, TGFβR2-negative prostate CAFs were found to increase CXCL1, CXCL16 and CXCL5 expression and facilitate prostate cancer cell adhesion to bone COL1 fibers to promote skeletal metastasis in C4-2B xenografts." (PMID 36671452, 2022). "The expression of CXCL16 and CXCR6 is also increased by the inflammatory response, in particular, by pro-inflammatory cytokines (TNF-α and IFN-γ) in prostate cancer cells." (PMID 33800554, 2021). "Multiple studies have reported increased expression of both CXCL16 and CXCR6 in advanced stages of prostate cancer as well as in metastatic tissues, with expression pattern correlating with Gleason score of patients." (PMID 32585812, 2020). "During the early phase of metastasis, cytokines such as TGFβ, IL-6, CXCL8, IL-7, CXCL16, and CX3CL1 induce EMT in prostate cancer cells and transforms them to exhibit higher migratory and invasive potentials." (PMID 32585812, 2020).
prostate carcinoma (continued). "CXCL16 and its receptor, CXCR6, have been found to possess functional roles in various stages of prostate cancer metastasis including EMT, invasion, and tumor cell homing to secondary sites." (PMID 32585812, 2020). "While mainly expressed by antigen-presenting cells, CXCL16 is also produced by bone tissues including osteocytes and was shown to be involved in migration of CXCR6 expressing prostate cancer cells to this site." (PMID 31338489, 2019). "Overall, our findings suggesting pro-tumorigenic roles for CXCL16 and CXCR6 in prostate cancer are consistent with these published reports." (PMID 19690611, 2009). "Immunohistochemistry and/or immunofluorescence and confocal imaging of 121 human prostate specimens showed that CXCL16 and CXCR6 were co-expressed, both on prostate cancer cells and adjacent T cells." (PMID 19690611, 2009). "Analysis of the 40-case array for levels of staining for CXCL16 and CXCR6 revealed that their expression by the cancer cells correlated with both high-stage and high-grade prostate cancer." (PMID 19690611, 2009). "Also, reduced CXCL16 expression increases the proliferation of non-small cell lung cancer A549 and NCI-H460 cells, as well as prostate cancer DU145 and PC3 cells." (PMID 33800554, 2021). "As alluded in a recent study, activation of the CXCL16/CXCR6 pathway promoted increased migration and invasion of prostate cancer cells via its ability to induce cytoskeletal protein reorganization through enhanced Ezrin phosphorylation and clustering of αvβ3 integrin structures." (PMID 32585812, 2020). "We found that CXCL16 and CXCR6 are expressed on T cells adjacent to prostate cancer cells." (PMID 19690611, 2009). "The co-expression of CXCL16 and CXCR6 on prostate cancer cells, and their correlation with cancer stage and grade, suggested that the ligand and receptor might enhance proliferation through an autocrine pathway." (PMID 19690611, 2009). "Our data correlating CXCL16 and CXCR6 with stage and grade of prostate cancer provide additional evidence that, in the prostate, inflammation is tumorigenic, and should stimulate the increasing interest in a possible tumor-promoting role specifically for CD4+ T cells." (PMID 19690611, 2009). "In prostate cancer cells, a CXCR6/CXCL16 pair may activate the PI3K/Akt signal pathway." (PMID 23941552, 2013). "This latter observation contrasts with our findings on the positive correlations between expression of CXCL16 and CXCR6 and high stage and grade for prostate cancer, and may reflect variable roles for inflammation in cancer depending on tumor type and stage of tumor development." (PMID 19690611, 2009). "In addition, a correlation between the expression levels of CXCL16 and CXCR6 was found by analyzing an array of forty cases of prostate cancer, and CXCL16 and CXCR6 can be shown to be co-expressed on individual cancer cells by immunofluorescent confocal microscopy." (PMID 19690611, 2009). "Our preliminary screen for chemokine expression suggested a role for CXCL16, and we found that both CXCL16 and CXCR6 were co-expressed on cancer cells, that their levels of expression correlated with each other, and that these levels also correlated with high-stage and high-grade prostate cancer." (PMID 19690611, 2009).
atherosclerosis (38 papers, 2008 to 2025). A disease characterized by the build-up of fatty material and calcium deposition in the arterial wall resulting in partial or complete occlusion of the arterial lumen. "A previous study showed that CXCL16 binds to oxidized low-density lipoprotein, suggesting it’s linked to atherosclerosis." (PMID 36531717, 2022). "The SR member, CXCL16, is a membrane-bound chemokine, which binds oxLDL and promotes proinflammatory responses linked to atherosclerosis development." (PMID 33182772, 2020). "Previous studies have established the close association between CXCL16 and the pathogenesis of atherosclerosis and MI." (PMID 28286356, 2017). "Mounting evidences have uncovered the close association of CXCL16 with the development of diverse human inflammatory diseases, including atherosclerosis, coronary artery disease, and MI." (PMID 28286356, 2017). "Therefore, we investigated the expression of CXCL16 on proinflammatory monocytes and its role in lipid uptake in psoriasis associated atherosclerosis and metabolic syndrome." (PMID 35784287, 2022). "Hofnagel and co-workers found that CXCL16 is expressed primarily in the endothelium at sites predisposed to atherosclerosis in the rabbit aorta; furthermore, anti-CXCL16 antibody treatment of primary human endothelial cells caused a significant reduction in endothelial-monocyte adhesion." (PMID 33182772, 2020). "CXCL16, as a proinflammatory cytokine, is closely associated with atherosclerosis incidence." (PMID 32676207, 2020). "However, dysregulation of the CXCR6/CXCL16 axis has been implicated in inflammatory conditions such as atherosclerosis and rheumatoid arthritis." (PMID 25888629, 2015). "By establishing a mouse model of CXCL16 overexpression, Zhao, Yang, and Wu further demonstrated that CXCL16 promotes atherosclerosis." (PMID 40165931, 2025). "CXC chemokine ligand 16 (CXCL16) expression is often observed in studies related to atherosclerosis (AS)." (PMID 40165931, 2025). "Beyond atherosclerosis, CXCL16 is involved in non-alcoholic fatty liver disease, inflammatory bowel disease, human immunodeficiency virus disease course, as well as tumorigenesis." (PMID 36555579, 2022). "A controversial role of the CXCL16/CXCR6 axis was found in atherosclerosis, suggesting that there exists a complex molecular mechanism between CXCL16/CXCR6." (PMID 33637127, 2021). "For this reason, more research is needed on the role of CXCL16 in the pathogenesis of atherosclerosis." (PMID 33800554, 2021). "While the role of the CXCL16–oxLDL interaction in atherosclerosis has been extensively studied, the biological relevance of PS as a ligand for CXCL16 remains poorly understood." (PMID 34038417, 2021). "Clinical studies have shown a significant increase in serum CXCL16 concentrations in patients with atherosclerosis." (PMID 35668739, 2021). "The frequency of non-classical monocytes positively correlated with the serum concentration of CXCL16, whose role in atherosclerosis remains controversial." (PMID 33854919, 2020). "We found a direct association between CD14 CD16hi monocytes and concentration of CXCL16,+ which goes in accordance with their controversial role in atherosclerosis." (PMID 33854919, 2020). "Studies in animals and humans showed that CXCL16 plays a key pro-inflammatory role in obesity and atherosclerosis, thereby increasing the progression of obesity." (PMID 32684073, 2020).